EXOSC3 (exosome component 3)
Description:
Non-catalytic component of the RNA exosome complex which has 3'->5' exoribonuclease activity and participates in a multitude of cellular RNA processing and degradation events. In the nucleus, the RNA exosome complex is involved in proper maturation of stable RNA species such as rRNA, snRNA and snoRNA, in the elimination of RNA processing by-products and non-coding 'pervasive' transcripts, such as antisense RNA species and promoter-upstream transcripts (PROMPTs), and of mRNAs with processing defects, thereby limiting or excluding their export to the cytoplasm. The RNA exosome may be involved in Ig class switch recombination (CSR) and/or Ig variable region somatic hypermutation (SHM) by targeting AICDA deamination activity to transcribed dsDNA substrates. In the cytoplasm, the RNA exosome complex is involved in general mRNA turnover and specifically degrades inherently unstable mRNAs containing AU-rich elements (AREs) within their 3' untranslated regions, and in RNA surveillance pathways, preventing translation of aberrant mRNAs. It seems to be involved in degradation of histone mRNA. The catalytic inactive RNA exosome core complex of 9 subunits (Exo-9) is proposed to play a pivotal role in the binding and presentation of RNA for ribonucleolysis, and to serve as a scaffold for the association with catalytic subunits and accessory proteins or complexes. EXOSC3 as peripheral part of the Exo-9 complex stabilizes the hexameric ring of RNase PH-domain subunits through contacts with EXOSC9 and EXOSC5.
Synonyms: RRP40; CGI-102; hRrp40p; Rrp40p; p10; hRrp-40; PCH1B; bA3J10.7
Tractability: Small molecule: a structure with a bound ligand is known. PROTAC: UniProt records ubiquitination sites on it; ubiquitination databases record sites on it.
Gene: Protein-coding gene on chromosome 9 (37,759,234 to 37,832,117, reverse strand). Ensembl gene ENSG00000107371.
Subcellular location: Cytoplasm; Nucleus, nucleolus; Nucleus
Subcellular location (Human Protein Atlas): Nucleoplasm
Pathways (Reactome):
Metabolism of RNA: Butyrate Response Factor 1 (BRF1) binds and destabilizes mRNA; KSRP (KHSRP) binds and destabilizes mRNA; Major pathway of rRNA processing in the nucleolus and cytosol; Nuclear RNA decay; Tristetraprolin (TTP, ZFP36) binds and destabilizes mRNA; mRNA decay by 3' to 5' exoribonuclease
Cellular responses to stimuli: ATF4 activates genes in response to endoplasmic reticulum stress
Gene Ontology:
Molecular function: protein binding; RNA exonuclease activity; 3'-5'-RNA exonuclease activity; RNA binding
Biological process: CUT catabolic process; DNA deamination; mRNA catabolic process; RNA catabolic process; RNA processing; rRNA processing; exonucleolytic trimming to generate mature 3'-end of 5.8S rRNA from tricistronic rRNA transcript (SSU-rRNA, 5.8S rRNA, LSU-rRNA); isotype switching; nuclear polyadenylation-dependent rRNA catabolic process; nuclear-transcribed mRNA catabolic process; poly(A)-dependent snoRNA 3'-end processing; TRAMP-dependent tRNA surveillance pathway; U4 snRNA 3'-end processing; DNA metabolic process; gene expression; regulation of gene expression
Cellular component: cytoplasm; cytoplasmic exosome (RNase complex); cytosol; euchromatin; exosome (RNase complex); nuclear exosome (RNase complex); nucleolus; nucleoplasm; nucleus; nucleolar exosome (RNase complex)
Genetic constraint (gnomAD): Loss-of-function variants: 18 observed, 24.9 expected, observed/expected ratio (o/e) 0.72, 90% interval 0.5 to 1.07. The upper end of that interval is the gene's LOEUF score, 1.07, which puts it in group 4 of 6, group 1 being the genes least tolerant of losing a copy. Missense variants: 382 observed, 354.02 expected, observed/expected ratio (o/e) 1.08, 90% interval 0.99 to 1.17. Synonymous variants: 165 observed, 133.93 expected, observed/expected ratio (o/e) 1.23, 90% interval 1.09 to 1.4.
Homologues: Orthologues: chimpanzee EXOSC3 (99% identical), macaque EXOSC3 (98% identical), pig EXOSC3 (92% identical), guinea pig EXOSC3 (91% identical), rabbit EXOSC3 (89% identical), rat Exosc3 (87% identical), mouse Exosc3 (87% identical), dog EXOSC3 (68% identical), tropical clawed frog exosc3 (61% identical), zebrafish exosc3 (54% identical), zebrafish wu:fc33b09 (54% identical), Drosophila melanogaster Rrp40 (35% identical), and 1 more. Paralogues in human: EXOSC2 (20% identical).
Diseases named in the same sentence as EXOSC3 in open-access papers:
EXOSC3 is named in the same sentence as 36 diseases in open-access papers, as found by Europe PMC text mining. Sharing a sentence is not in itself a finding about the gene and the disease. The quoted sentences say what the papers report.
pontocerebellar hypoplasia type 1B (8 papers, 2014 to 2026). "In a separate group with pontocerebellar hypoplasia type 1B, six Roma patients (three males, three females) shared the same EXOSC3 mutation." (PMID 42195294, 2026). "Mutations in the RNA exosome component 3 (EXOSC3) gene cause Pontocerebellar Hypoplasia Type 1b (PCH1b), an autosomal recessive neurologic disorder." (PMID 32645003, 2020). "The first such example was the finding that recessive mutations in the EXOSC3 gene, encoding a structural RNA exosome cap subunit, cause a neurologic disease termed Pontocerebellar Hypoplasia type 1b (PCH1b)." (PMID 32645003, 2020). "Recently, mutations affecting EXOSC3, the human homolog of Rrp40p, were shown to cause pontocerebellar hypoplasia type 1B (PCH1B, OMIM614678)." (PMID 28053271, 2017). "Variants of exosome component 3 (EXOSC3), exosome component 8 (EXOSC8) and exosome component 9 (EXOSC9) have all been associated with pontocerebellar hypoplasia type 1 (PCH1B-D)." (PMID 40428407, 2025). "Pontocerebellar hypoplasia type 1B (PCH1B) is a severe autosomal recessive neurologic disorder causing cerebellar and spinal motor neuron degeneration at birth caused by a mutation in the EXOSC3 gene (MIM606489)." (PMID 40182349, 2025).
pontocerebellar hypoplasia (7 papers, 2018 to 2023). Pontocerebellar hypoplasias (PCH) are a rare heterogeneous group of diseases characterized by hypoplasia and atrophy and/or early neurodegeneration of the cerebellum and pons. "Recessive variants in exosome components EXOSC3, EXOSC8, and RBM7 cause various constellations of pontocerebellar hypoplasia (PCH), spinal muscular atrophy (SMA), and central nervous system demyelination." (PMID 29727687, 2018). "Recently, pathogenic variants in genes encoding both structural and catalytic subunits of the RNA exosome have been linked to human disease, such as EXOSC3 and EXOSC8 related forms of pontocerebellar hypoplasia, representing recessive neurodegenerative diseases." (PMID 34944310, 2021). "Mutations in EXOSC3, EXOSC8, and EXOSC9 cause several forms of autosomal-recessive neurodegenerative disease, pontocerebellar hypoplasia (PCH), namely, PCH type 1b (PCH1b), PCH1c, and PCH1d, respectively." (PMID 34948199, 2021). "Recessive variants in exosome components EXOSC3, EXOSC8, and RBM7 cause various constellations of pontocerebellar hypoplasia (PCH), spinal muscular atrophy (SMA), and central nervous system hypomyelination." (PMID 34573300, 2021).
pancreatic cancer (3 papers, 2022 to 2024). "A previous study showed that the protein expression of EXOSC3 was significantly up-regulated in pancreatic cancer tissue using protein-deep sequencing, but there were no published studies that explored the associations between genetic variants of EXOSC3 and NSCLC survival." (PMID 39176091, 2024). "Ansari and his colleagues revealed that EXOSC3 was significantly upregulated in pancreatic cancer tissue using protein deep sequencing." (PMID 36032660, 2022). "We found that knockdown of EXOSC10, but not EXOSC3 or EXOSC9, caused growth inhibition of pancreatic cancer cells." (PMID 35008922, 2022).
spinal muscular atrophy (3 papers, 2016 to 2021). A motor neuron disease that affect the muscles, and characterized by muscle weakness and atrophy resulting from progressive degeneration and irreversible loss of the anterior horn cells in the spinal cord (i.e., lower motor neurons) and the brain stem nuclei. "Mutations in its subunits EXOSC8 and EXOSC3 cause pontocerebellar hypoplasia, spinal muscular atrophy (SMA) and central nervous system demyelination." (PMID 27193168, 2016).
breast carcinoma (2 papers, 2022). "The univariate and multivariate Cox regression analysis revealed that six CDM genes (SRF, RAD51, PMF1, EXOSC3, EXOC1 and TSEN54) were associated with the survival of patients with breast cancer." (PMID 35096059, 2022). "Six CDM genes (SRF, RAD51, PMF1, EXOSC3, EXOC1, and TSEN54) were found to be associated with the prognosis of breast cancer samples." (PMID 35096059, 2022). "A recent study reported that EXOSC4 knockdown resulted in the downregulation of other RNA exosome components, EXOSC3 and EXOSC9, at the protein level in MDA-MB-231 cells, a breast cancer cell line." (PMID 35008922, 2022).
Intellectual disability (2 papers, 2014 to 2024). "For example, loss of EXOSC3 or EXOSC9 gene function has been associated with a neurodevelopmental syndrome that includes intellectual disability and axon degeneration during infancy." (PMID 39480871, 2024). "Moreover, mutations in EXOSC3 and EXOSC9 are also associated with intellectual disability in humans and mutations in EXOSC8 causes behavioral defects in zebrafish." (PMID 39480871, 2024).
Cerebellar atrophy (1 paper, 2018). Cerebellar atrophy is defined as a cerebellum with initially normal structures, in a posterior fossa with normal size, which displays enlarged fissures (interfolial spaces) in comparison to the foliae secondary to loss of tissue. "The involvement of spinal motor neurons together with cerebellar atrophy, with or without pontine involvement, is a common feature in affected individuals with variants in different exosomal subunit (EXOSC3, EXOSC8, and EXOSC9) and belongs to the spectrum of PCH1-related disorders." (PMID 29727687, 2018).
Cerebellar hypoplasia (1 paper, 2020). Cerebellar hypoplasia is a descriptive term implying a cerebellum with a reduced volume, but a normal shape and is stable over time. "A recent paper reported that human patients with mutations that decrease EXOSC9 expression show cerebellar hypoplasia similar to that observed with mutations in other RNA exosome components such as EXOSC3 and EXOSC8 genes." (PMID 32518284, 2020).
MELAS (1 paper, 2021). "Consecutive MRIs were performed in 17 patients and imaging evidence of disease progression was present in 11 patients [six patients with MELAS, two patients with POLG1, and the patients with MERRF, exosome component 3 (EXOSC3), and dynamin-like protein 1 (DNM1L)]." (PMID 34912288, 2021).
Progressive encephalopathy (1 paper, 2022). "Lastly, two patients, MD-122 and MD-012 (homozygous EXOSC3 p.D132A), suffered from progressive encephalopathy with spasticity, muscular weakness, and early and rapid vermis atrophy." (PMID 36233161, 2022).
progressive neurodegenerative disorder (1 paper, 2016). "Loss-of-function mutations in the EXOSC3 gene, encoding the RRP40 RNA exosome protein, are a cause of the inherited progressive neurodegenerative disorder pontocerebellar hypoplasia." (PMID 27242399, 2016).
neurological disorders (4 papers, 2017 to 2024). "The first link between the RNA exosome complex and disease described a patient with a missense mutation in EXOSC3, which causes the neurological disease pontocerebellar hypoplasia type 1B." (PMID 38219817, 2024). "To investigate the molecular consequences of mutations in EXOSC3 that lead to neurological diseases, we analyzed the effect of three of the mutations that affect conserved residues of EXOSC3/Rrp40p (G31A, G191C, and W238R; G8A, G148C, and W195R, respectively, in human and yeast) in S. cerevisiae." (PMID 28053271, 2017).
cancer (3 papers, 2016 to 2024). A tumor composed of atypical neoplastic, often pleomorphic cells that invade other tissues. "Genes encoding exosome complex components are linked to pathologies including cancer (DIS3), immune disorders (EXOSC9 and EXOSC10) and congenital neurological disorders (EXOSC3 and EXOSC8)." (PMID 27543448, 2016).
infection (1 paper, 2015). The state of being infected such as from the introduction of a foreign agent such as serum, vaccine, antigenic substance or organism. "Binding of Matrin 3 to DDX17, EXOSC3, and ZAP in uninfected cells may reflect a role for Matrin 3 in alternate host RNA processes, but during infection Matrin 3 may impede ZAP from interacting with these proteins which are needed for optimal RNA degradation activity." (PMID 26129669, 2015). "HIV-luc infection did not increase protein levels of DDX17, EXOSC3, or myc-ZAP2." (PMID 26129669, 2015).
tumor (1 paper, 2022). "SRF and EXOSC3 expression levels were lower in tumor tissues than in control tissues, while RAD51 and EXOC1 were significantly higher in tumor tissues." (PMID 35096059, 2022).
EXOSC3 also shares sentences with these, for which no sentence is quoted: Ataxia (2 papers); butyrylcholinesterase deficiency (1); Cerebellar cyst (1); cerebellar degeneration (1); Ehlers-Danlos syndrome (1); Encephalopathy (1); genetic diseases (1); glaucoma (1); Hypertonia (1); Hypotonia (1); immune disorders (1); MEGDEL syndrome (1); MERRF (1); microcephaly (1); Miller syndrome (1); mitochondrial disease (1); neurodegenerative disease (1); Neurodevelopmental delay (1); non-small cell lung carcinoma (1); Parkinson ́s disease (1); spastic paraplegia type 7 (1).